HOTAIR (HOX transcript antisense RNA)
Diseases named in the same sentence as HOTAIR in open-access papers (continued):
Sharing a sentence is not in itself a finding about the gene and the disease.
breast cancer (continued). "For example, the interaction of HOTAIR with PRC2 or LSD1 can be inhibited by HOTAIR targeting small molecular inhibitors, thereby reducing the metastasis of breast cancer." (PMID 31214490, 2019). "Several miRNAs were also reported to regulate growth of breast cancer cells through inhibiting HOTAIR." (PMID 30429228, 2019). "In this study, we demonstrated that lncRNA HOTAIR plays a critical role in radiation resistance of breast cancer cells." (PMID 30429228, 2019). "HOTAIR up-regulation has also been determined in many types of malignant tissue and cell, including breast cancer." (PMID 31796041, 2019). "For example, HOTAIR is a lncRNA that is highly expressed in HER2+ breast cancers whereas HOTAIRM1 is highly expressed in basal‐like subgroup of breast cancers." (PMID 30959550, 2019). "Among all lncRNAs, HOTAIR was up-regulated in many cancers, including gastrointestinal stromal tumors, cervical cancer, lung cancer, as well as breast cancer." (PMID 30429228, 2019). "Genistein modulates the expression level of HOTAIR in breast cancer, which consequently modulates the activity of the PI3K/Akt signaling pathway." (PMID 31208095, 2019). "First, we examined the expression of HOTAIR in 10 paired breast cancer tissues and found that HOTAIR increased significantly in cancer tissues, compare with the normal tissues." (PMID 30429228, 2019). "Among those studies, the analysis of the lncRNA expression profile of breast cancer samples in TCGA revealed different subtypes of breast cancer and subtype-specific overexpression of HOTAIR." (PMID 31808800, 2019). "Among these reports, few investigations have indicated overexpression of HOTAIR transcript in the breast cancer patients’ peripheral blood." (PMID 31796041, 2019). "Recently, several studies have demonstrated that lncRNA HOTAIR was involved in the regulation of breast cancer proliferation, metastasis, and invasion." (PMID 30429228, 2019). "For instance, the breast cancer-related lncRNA HOTAIR is silent in most cancer patients, and is highly expressed in only a few of tumor types, most of which are breast cancers." (PMID 31877126, 2019). "Previous studies have shown that HOTAIR is elevated in lung cancer, breast cancer, liver cancer, and so on and correlates with metastasis and poor prognosis." (PMID 31281803, 2019). "Briefly, they compared serum exosomal HOTAIR expression levels between 15 breast cancer patients and 15 healthy individuals, demonstrating a significantly higher expression in breast cancer patients than in healthy controls." (PMID 35582278, 2019). "Curcumin also caused the modulation of tumor suppressor HOTAIR in pancreatic cancer, prostate cancer, hepatocellular carcinoma (HCC), nasopharyngeal carcinoma (NPC), breast cancer, lung cancer, and renal cancer." (PMID 31208095, 2019). "We have recently aimed to investigate regulation of HOTAIR in the whole peripheral blood (including circulating as well as white blood cell RNA) of breast cancer patients compared to normal individuals." (PMID 31796041, 2019). "With this mechanism HOTAIR can guide PRC2 to target genes related with tumor metastasis in breast cancer." (PMID 31072041, 2019). "Our data showed that HOTAIR (HOX antisense intergenic RNA) was up-regulated in breast cancer cells and tissues, and the expression of HOTAIR increased following irradiation." (PMID 30429228, 2019). "Previous study has also demonstrated that small peptides targeting HOTAIR inhibited growth of breast cancer cells." (PMID 30429228, 2019). "In conclusion, our data showed that lncRNA HOTAIR was up-regulated in breast cancer, and HOTAIR inhibition resulted in a radiosensitive phenotype." (PMID 30429228, 2019). "It seems that the upregulation of HOTAIR has a controversial effect in terms of the occurrence of different cancer types and response to therapy methods, so radioresistance in breast cancer is enhanced by upregulated HOTAIR." (PMID 31208095, 2019).
breast cancer (continued). "TGFβ1 secreted by CAFs induces epithelial-mesenchymal transition and metastasis of breast cancer through HOTAIR." (PMID 31448238, 2019). "In the present study, we found that lncRNA was up-regulated in breast cancer cells, and knockdown of HOTAIR increased cell apoptosis induced by IR." (PMID 30429228, 2019). "HOTAIR has an important function in ECM signaling in breast cancer, above all in invasive “claudin low” molecular subtype." (PMID 31072041, 2019). "On April 2015, findings published in the “Journal of Translational Medicine” suggested up-regulation of HOTAIR expression in the breast cancer tissues and cell lines, through inhibiting miR-148 by estrogenic GPER signalling activity." (PMID 31796041, 2019). "In 2016, an article was published in the “Thoracic Cancer” journal suggesting overexpression of HOTAIR in circulating peripheral blood of breast cancer patients." (PMID 31796041, 2019). "In the present study, we found that down-regulation of HOTAIR sensitizes breast cancer cells to ionizing radiation through regulation on miR-218, which provided novel mechanism and target for breast cancer radiotherapy." (PMID 30429228, 2019). "In human breast cancer cell lines, siRNA-mediated downregulation of HOTAIR inhibited cancer cell viability and matrix invasion." (PMID 31448238, 2019). "HOTAIR is highly expressed in ER-positive, tamoxifen- resistant breast cancer cell line and in tissue samples from recurrent patients failed to tamoxifen treatment." (PMID 31882666, 2019). "One of the few-reported observations on HOTAIR transcriptional regulation includes characterization in human breast cancer cells of an enhancer, termed HOXC Distal Enhancer (HDE) located 150 Kb downstream of the HOTAIR TSS." (PMID 30154449, 2019). "Among them, HOX transcriptional antisense RNA (HOTAIR) gene is most closely related to breast cancer." (PMID 30828265, 2019). "The lncRNA HOTAIR is upregulated in primary breast cancers and metastases, and the HOTAIR expression level in primary cancers also serves as a promising predictor of eventual metastasis and death." (PMID 31340867, 2019). "Recent studies indicated that HOTAIR promoted the invasion of breast carcinoma cells in a PRC2-dependent manner." (PMID 30764859, 2019). "A comparative breast cancer study of profiling lncRNA have shown that expression of HOTAIR is sufficient to drive breast cancer metastasis." (PMID 30197753, 2018). "And the breast cancer microenvironment plays a key role in maintaining HOTAIR expression in cancer cells." (PMID 29325547, 2018). "HOTAIR was the first lncRNA shown to promote tumour progression and be related to poor prognosis in breast cancer." (PMID 28941134, 2018). "Previous reports indicated that higher expression of HOTAIR is correlated with a higher resistance to radiotherapy in colon and breast cancer cell lines." (PMID 30441874, 2018). "The lncRNA HOTAIR is found overexpressed in a number of cancers, including breast cancers, and redirects PRC2 and LSD1, impacting global chromatin architecture." (PMID 30306389, 2018). "This overexpression of HOTAIR was positively correlated with DNA methylation in primary breast cancer." (PMID 29732012, 2018). "The influence of HOTAIR expression on overall survival was analyzed in a cohort of 132 breast cancer patients." (PMID 30687231, 2018). "With respect to breast cancer, HOTAIR and its elevated levels in breast cancer acts as a marker for metastasis." (PMID 29732012, 2018). "Our studies provide a strong body of evidence to support that the modulation of epigenetic control and targeted alterations of HOTAIR represent novel therapeutic targets in breast cancer." (PMID 29325547, 2018). "For example, over-expression of the lncRNA HOTAIR in breast cancer patients is reported to be highly predictive of patient survival and progression to metastasis." (PMID 30180792, 2018).
breast cancer (continued). "In ERα-positive as well as in triple-negative, breast cancer cell lines' expression of HOTAIR was induced by 17β-estradiol as another GPER-dependent signaling event." (PMID 30687231, 2018). "Another hallmark example is HOTAIR, which is encoded in the HOXC cluster and is a strong predictor of breast cancer metastasis." (PMID 30197753, 2018). "Our findings demonstrated that CAFs promoted the metastatic activity of breast cancer cells by activating the transcription of HOTAIR via TGF-β1 secretion, supporting the pursuit of the TGF-β1/HOTAIR axis as a target in breast cancer treatment." (PMID 29325547, 2018). "Studies pointed out that lncRNA HOTAIR is overexpressed in breast cancer tissues compared with adjacent normal counterparts." (PMID 30111807, 2018). "Previous studies from our laboratory showed that HOTAIR is required for the viability of breast cancer cells and its expression is regulated by estradiol and hypoxia." (PMID 30353135, 2018). "Overall, we describe the epigenetic mechanisms underlying the CAF-induced aggressive behavior of cancer cells, which support the targeting of the TGF-β1/ HOTAIR axis as a novel strategy for breast cancer treatment." (PMID 29325547, 2018). "Given its critical role during tumor progression, HOTAIR is a novel target for breast cancer therapy." (PMID 29325547, 2018). "Overexpression of HOTAIR in breast cancer cell lines promotes its proliferation, migration, and invasion." (PMID 29941860, 2018). "Experimentally, in vivo and in vitro overexpression of HOTAIR increases the invasive nature of breast cancer cells." (PMID 29732012, 2018). "HOTAIR (HOX transcript antisense RNA) is known as a functional lncRNA which participates in several tumor types including breast cancer." (PMID 29423075, 2018). "Based on our results, we propose a model of the CAF-mediated upregulation of HOTAIR transcription in breast cancer cells that promotes invasion and metastasis via the secretion of TGF-β1." (PMID 29325547, 2018). "We suppose, that similar to colon and breast cancers cell lines, up-regulation of HOTAIR is probably responsible for radioresistance of HNSCC cell lines." (PMID 30441874, 2018). "Firstly, aberrant up-regulation of HOTAIR was found in breast cancer tissue or plasma samples compared with normal adjacent non-tumorous tissue or healthy controls." (PMID 29423075, 2018). "HOTAIR has been widely explored in breast cancer and suggested as a functional lncRNA which is correlated with the carcinogenesis, progression and prognosis of BC." (PMID 29423075, 2018). "In breast cancer, increasing evidences have suggested that lncRNA HOTAIR is an oncogene which is correlated with the BC carcinogenesis, progression and prognosis." (PMID 29423075, 2018). "This overlapping implies in sis action of HOTAIR in breast cancer besides its established in trans action via binding to PRC2." (PMID 28846832, 2017). "The carcinogenic action of HOTAIR was confirmed in breast cancer stem-like cells, in which it was essential for self-renewal and proliferation." (PMID 29469819, 2017). "Overall, here we illustrate a novel mechanism by which HOTAIR modulates cell proliferation via miR-206 targeting Bcl-w in breast cancer." (PMID 29222472, 2017). "The results can highlight the role of HOTAIR in breast invasive cancer and provide the viewpoint for further analyses of HOTAIR in breast cancer progression." (PMID 29209357, 2017). "In turn, decreased Akt activation by its decreased phosphorylation increased IRF1 and diminished HOTAIR expression in MCF-7 breast cancer cells." (PMID 29469819, 2017). "Many downstream molecules of HOTAIR have been identified: in breast cancer, HOTAIR increases cancer invasiveness and metastasis in a manner dependent on PRC27." (PMID 28931862, 2017). "HOTAIR expression is transcriptionally induced by estradiol in the MCF7 breast cancer cell line, and its promoter contains multiple estrogen response elements." (PMID 29127278, 2017).
breast cancer (continued). "Given the importance of HOTAIR in breast cancer, it promises as a potential biomarker and therapeutic target." (PMID 29209357, 2017). "The Up-regulation of HOTAIR in breast cancer samples (case) compared to normal samples (controls) in different GEO datasets." (PMID 29209357, 2017). "Thereby, administration of genistein supports anti-cancer effects, reducing cell proliferation, migration and apoptosis trough down-regulation of oncogenic HOTAIR, in both prostate and breast cancer pathologies." (PMID 28587155, 2017). "We set out to explore ECM‐mediated regulation of expression of the lncRNA HOTAIR in Claudin‐low breast cancer cells using lrECM 3D culture." (PMID 28846832, 2017). "Taken together, we conclude that HOTAIR promotes cell proliferation through regulating miR-206/Bcl-w in breast cancer." (PMID 29222472, 2017). "When targeting the HOTAIR–miRNA axis in breast cancer therapy, it is important to limit the number of miRNAs to those, which are specific or enriched in this disease." (PMID 29469819, 2017). "Circulating DNA of the HOTAIR gene is considered as a marker in breast cancer, which was shown in a population-based study." (PMID 29469819, 2017). "For instance, HOTAIR is upregulated in breast cancer, cervical cancer cells, CRC, pancreatic ductal adenocarcinoma (PDAC) and Lewis lung cancer." (PMID 28872613, 2017). "A correlation between the expression of EZH2 and HOTAIR in breast cancer was observed in a high throughput tissue microarray study." (PMID 29469819, 2017). "The promoter binding by the histone methylases MLL1 and MLL3 and CBP/p300, which are histone remodeling factors in an E2-dependent manner can be important for the epigenetic functions of HOTAIR in breast cancer." (PMID 29469819, 2017). "For example, the lncRNA HOTAIR is dysregulated in several cancers, including colon, breast, pancreas, and liver cancers, and the overexpression of HOTAIR has been shown to drive breast cancer metastasis." (PMID 28051121, 2017). "Recently, lncRNAs such as lncRNA-ATB, GAS5, HOTAIR, CCAT2, H19, BCAR4, UCA1, LncRNA-ROR and LncRNA-ARA have been implicated in resistance to chemotherapy in breast cancer patients." (PMID 29299178, 2017). "Such one is HOTAIR, lots of studies have shown that HOTAIR is overexpressed in colorectal cancer, pancreatic cancer, breast cancer, gastric cancer and gastrointestinal stromal tumors and is positively correlated with a poor clinical outcome." (PMID 28209170, 2017). "A decrease in migration and invasiveness of breast cancer MCF-7 cells was associated with a decreased expression of MMPs 2 and 9 in these cells, in which HOTAIR was downregulated by siRNA." (PMID 29469819, 2017). "Although our findings were mainly from ER positive breast cancer cells, the relationship between the classification and the main factors (HOTAIR, Bcl-w and miR-206) still need more evidence to prove." (PMID 29222472, 2017). "HOTAIR also transcriptionally inhibits the expression of miR-568 by directly targeting NFAT5 that promotes EMT in breast cancer." (PMID 27992370, 2017). "Previous studies have shown that HOTAIR plays an important role in many tumors including prostate cancer, gastric cancer, cervical cancer, and breast cancer." (PMID 28108736, 2017). "HOTAIR overexpression promotes breast cancer cell proliferation, whereas its depletion significantly impairs cell survival and abolishes tamoxifen-resistant cell growth." (PMID 28938586, 2017). "In breast cancer stem cells, HOTAIR has been shown to contribute to the proliferation, migration, colony formation, and self-renewal capacities through transcriptionally inhibiting miR-34a of breast CSCs, leading to upregulation of Sox2." (PMID 29228709, 2017). "One of the most well characterized lincRNAs, HOTAIR, was identified in primary and metastatic breast cancers and its expression level is a powerful predictor of patient survival." (PMID 28423633, 2017).
breast cancer (continued). "The aim of this study was to examine the significance of the HOTAIR gene expression in breast cancer." (PMID 29209357, 2017). "In accordance, an EMT‐like derivative of the human breast cancer MCF‐7 cells exhibited a robust increase in HOTAIR expression and such an increase was required for accelerated proliferation and resistance to cell death." (PMID 28846832, 2017). "This important work not only confirms earlier reports on the importance of HOTAIR in breast cancer transformation and its clinical usefulness in diagnosis, prognosis, and therapy, but also shows many details of the mechanism of HOTAIR action." (PMID 29469819, 2017). "A recent report reveals that HOTAIR in breast cancer cell lines including ER positive breast cancer MCF-7 cells is higher than those in immortalized breast HBL-100 cells." (PMID 29222472, 2017). "In summary, our results indicate that HOTAIR expression is activated by BRD4 binding to a novel HOTAIR‐N promoter in Claudin‐low breast cancer cells that are attached to ECM." (PMID 28846832, 2017). "HOTAIR expression in breast cancer cells seems to re-impose the polycomb binding profile of an embryonic fibroblast thereby silencing metastasis suppressor genes and favouring a gene expression program that is conducive to cell motility and matrix invasion." (PMID 28587163, 2017). "Functionally, HOTAIR accelerated cell proliferation through miR-206 targeting Bcl-w in breast cancer." (PMID 29222472, 2017). "More importantly, our results indicate that HOTAIR expression is required for invasive growth of Claudin‐low breast cancer cells, particularly cell viability." (PMID 28846832, 2017). "Our finding takes a further step into the mechanism of lincRNA HOTAIR-mediated breast cancer growth." (PMID 29222472, 2017). "Induction of HOTAIR is required for invasive growth of Claudin‐low breast cancer cells in lrECM 3D culture." (PMID 28846832, 2017). "Initial studies using MALAT1 siRNAs demonstrated inhibition of cell migration, growth, and invasion in prostate cancer cells, while siRNAs directed against HOTAIR have been shown to reduce matrix invasion in breast cancer cells." (PMID 28829354, 2017). "Herein, we aimed to understand epigenetic regulation of the lncRNA HOTAIR by ECM in Claudin‐low breast cancer cells using lrECM 3D culture." (PMID 28846832, 2017). "One intriguing observation in the discovery of HOTAIR in breast cancer is that the RNA levels of HOTAIR in breast cell lines in cell culture are significantly lower than those observed in primary and metastatic breast tumors." (PMID 28846832, 2017). "HOTAIR can regulate autophagy, important for breast cancer cells survival, through the interaction with miRNAs specific for autophagy genes and directly with these genes." (PMID 29469819, 2017). "HOTAIR is aberrantly expressed in a variety of human cancers, such as breast cancer, colorectal cancer, laryngeal squamous cell carcinoma, and liver cancer." (PMID 28118613, 2017). "Our results indicate that HOTAIR, a classic example of tumor‐promoting lncRNA, is induced in lrECM 3D culture of Claudin‐low breast cancer cells, and such induction requires the canonical ECM signaling pathway, namely integrins and Src kinase." (PMID 28846832, 2017). "Herein, we demonstrate that the lncRNA HOTAIR is induced in lrECM 3D culture of Claudin‐low breast cancer cells over conventional 2D culture." (PMID 28846832, 2017). "These important studies suggest a significant role of HOTAIR in breast cancer pathogenesis and its large potential in diagnosis and therapy of this disease." (PMID 29469819, 2017). "Clinical studies have shown that the expression of HOTAIR is closely related to the metastasis, recurrence, and prognosis of breast cancer, colon cancer, and liver cancer; however, few studies have examined the role of HOTAIR expression in cervical cancer." (PMID 27897239, 2016).